Y_RNA (Y RNA )
Gene: Miscellaneous RNA gene on chromosome X (117,914,244 to 117,914,345, reverse strand). Ensembl gene ENSG00000200291.
Homologues: Orthologues: chimpanzee Y_RNA (98% identical), guinea pig Y_RNA (90% identical). Paralogues in human: RNY3 (90% identical), Y_RNA (89% identical), Y_RNA (88% identical), RNY3P1 (87% identical), Y_RNA (87% identical), RNY3P14 (86% identical), Y_RNA (86% identical), Y_RNA (85% identical), RNY3P11 (84% identical), RNY3P16 (84% identical), Y_RNA (84% identical), RNY3P9 (83% identical), and 97 more.